MTOR (mechanistic target of rapamycin kinase)
Diseases named in the same sentence as MTOR in open-access papers (continued):
Sharing a sentence is not in itself a finding about the gene and the disease.
pancreatic neuroendocrine tumor (continued). "Most recently, new drugs such as everolimus, an oral inhibitor of mammalian target of rapamycin (mTOR), and sunitinib, a tyrosine kinase inhibitor, have shown efficacy in controlling NETs, and in particular, pancreatic NET." (PMID 24053191, 2013). "Everolimus, an oral inhibitor of mammalian target of rapamycin (mTOR), has activity against pancreatic NET tumours through a mechanism of cellular apoptosis and antiangiogenesis." (PMID 22518323, 2012). "The efficacy of the mTOR inhibitor everolimus in pancreatic NETs was determined." (PMID 37387515, 2023). "Therapy options for advanced pancreatic neuroendocrine tumors (pNETs) include the mTOR inhibitor everolimus and peptide receptor radionuclide therapy (PRRT) with [177Lu]Lu-DOTA-TATE, however further optimization in the therapeutic landscape is required as response rates are still low." (PMID 36551858, 2022). "Pancreatic ductal adenocarcinoma cells, leukemic cells, and pancreatic neuroendocrine tumor cells all displayed comparable effects, and in both subtypes of pancreatic cancer, concurrent treatment with mTOR inhibitors enhanced the antiproliferative effects of NAMPT inhibition." (PMID 36160449, 2022). "Also, everolimus, an oral inhibitor of the mTOR pathway, and sunitinib, an oral multi-targeted tyrosine kinases inhibitor have been shown to improve progression-free survival in metastatic entero-pancreatic neuroendocrine tumors." (PMID 32903471, 2020). "mTOR signaling is frequently dysregulated in pancreatic neuroendocrine tumors (PNETs)." (PMID 30285764, 2018). "And it has been preclinically showed that deficiency of TSC2 or PTEN expression induces impaired PI3K/Akt/mTOR activation, suggesting that mTOR overexpression with the loss of PTEN plays a key role in the development and progression of pancreatic neuroendocrine tumors." (PMID 29642873, 2018). "In pancreatic NETs (pNETs), mutations of the epigenetic regulators MEN1 and DAXX/ATRX have been described in 44% and 43% of tumors respectively, while alterations of the mammalian target of rapamycin (mTOR) pathway have been found in 14% of the specimens." (PMID 27418145, 2016). "In addition to PDA, emerging evidence supports that PI3kinase/mTOR pathways are critical in pancreatic neuroendocrine tumors (PanNETs) due to PTEN deletion, tuberous sclerosis complex mutation and activation of Akt and mTOR." (PMID 25476893, 2015). "Recent studies have also reported that the tyrosine kinase inhibitor sunitinib and the mTOR inhibitor everolimus improved progression-free survival in patients with pancreatic NET, further expanding the therapeutic arsenal available to patients with this disease." (PMID 21672194, 2011). "For instance, 40 patients (8.1%) with pancreatic NETs may have benefited from mTOR inhibitors." (PMID 35267427, 2022). "The authors also found that pancreatic NETs exhibit recurrent genetic inactivation of MEN1, ATRX, and DAXX and the activation of the PI3K/mTOR pathway." (PMID 40026252, 2025). "Recently, the FDA approved a few targeted agents for pancreatic NETs including sunitinib, a multi-tyrosine kinase inhibitor, and everolimus, an inhibitor of the PI3K-Akt-mTOR signal pathway." (PMID 26684240, 2016).
pancreatic neuroendocrine tumor (continued). "The success of these two agents in pancreatic NETS supports the notion that targeting angiogenesis and/or PI3K/AKT/mTOR pathway is an important strategy for making therapeutic advances in this disease." (PMID 26609460, 2015). "A gene expression profile study of sporadic pancreatic NETs revealed down regulation of TSC2 and PTEN, two key inhibitors of the AKT/mTOR pathway in most of the sporadic NETs." (PMID 24626055, 2014). "Studies of biologically targeted therapies in pancreatic NET have, to date, focused primarily on inhibitors of the VEGF or mTOR signaling pathways." (PMID 21672194, 2011). "FTO-induced APOE activates the PI3K/AKT/mTOR signaling pathway by regulating the ubiquitination state of FASN, which enhances lipid metabolism and proliferative capacity, thereby promoting the malignant progression of pancreatic neuroendocrine tumors." (PMID 40764609, 2025). "Pancreatic NETs (PanNETs) have been among the most studied, and research so far has outlined a series of recurring features, as inactivation of MEN1, VHL, TSC1/2 genes and hyperactivation of the PI3K/mTOR pathway." (PMID 29321190, 2018). "In addition, engrafted rat pancreatic neuroendocrine tumors (PNET) exhibit increased tumor growth following treatment with an mTOR inhibitor, a response that contrasts the results of mTOR inhibitor clinical trials." (PMID 28879168, 2017). "Notably, in pancreatic neuroendocrine tumors targeting of both PI3K and mTOR was required to generate inhibitory effects on cells that were resistant to the mTORC1 inhibitor RAD001." (PMID 25823922, 2015). "The mTOR inhibitor Everolimus, and the multi-target antiangiogenetic agent Sunitinib, have been shown to be effective and thus have been approved by the FDA for treatment of pancreatic endocrine tumors." (PMID 23344019, 2012). "In addition, the insulin-regulated PI3K-Akt-mTOR pathway plays an important role in the regulation of islet cell proliferation, and this pathway is hyperactivated in human non-functional pancreatic neuroendocrine tumors (PanNETs)." (PMID 37679316, 2023). "To date, in vivo studies on pancreatic NETs have shown efficacy towards epigenetic modulators such as bromo- and extra terminal domain (BET) inhibitors, Wnt pathway targeting β-catenin antagonists, VEGF-signalling and mammalian target of rapamycin (mTOR) antagonists." (PMID 32326947, 2020).
acute lymphoblastic leukemia (82 papers, 2009 to 2025). Leukemia with an acute onset, characterized by the presence of lymphoblasts in the bone marrow and the peripheral blood. "Activation of the mTOR pathway is associated with deregulated production of malignant lymphoid cells and chemotherapeutic resistance in acute lymphoblastic leukemia (ALL)." (PMID 36980552, 2023). "The mechanistic target of rapamycin (mTOR) is a kinase whose activation is associated with poor prognosis in pre-B cell acute lymphoblastic leukemia (B-ALL)." (PMID 34737376, 2021). "RAD001 (everolimus), an mTOR inhibitor, also blocks cell survival in childhood acute lymphoblastic leukemia by inducing autophagy." (PMID 40573272, 2025). "Another study revealed a correlation between elevated mTOR and phosphorylated mTOR (p‐mTOR) levels and an increased likelihood of relapse in pediatric acute lymphoblastic leukemia (ALL)." (PMID 40754657, 2025). "The potential of ORI with imatinib was reported on Ph(+) acute lymphoblastic leukemia cells where ORI hindered LYN/mTOR signaling pathway activation and indicated a mutual antileukemia effect with imatinib." (PMID 38726411, 2024). "A previous study established a correlation between CDK8 and the mTOR pathway in acute lymphoblastic leukemia, suggesting that CDK8 regulates protein synthesis not only within a subset of MB but also in other types of cancer." (PMID 39574899, 2024). "Our analysis also gave BCL2 inhibitors associated with SF1126 or sirolimus (both MTOR inhibitors), and this combination of BCL2 with MTOR inhibitors is used in resistant acute lymphoblastic leukemia." (PMID 34864885, 2022). "Of interest, it has previously been reported that corticosteroid resistance in T-lineage acute lymphoblastic leukemia is associated with the upregulation of glycolysis and activation of PI3K/Akt/mTOR signaling." (PMID 31636329, 2019). "The combination of mTOR inhibitors and methotrexane were tested in acute lymphoblastic leukemia where it was synergistically effective." (PMID 30564554, 2018). "It was reported that DEX is an inductor of autophagy in lymphoblastic leukaemia cells as well as in rat skeletal muscles, and the activation of mTOR signalling pathway is suggested." (PMID 28827819, 2017). "Other scholars find that rapamycin sensitizes glucocorticoid-resistant acute lymphoblastic leukemia CEM-C1 cells to dexamethasone-induced apoptosis through both mTOR suppression and upregulation and activation of glucocorticoid receptor." (PMID 29047405, 2017). "Inhibition of the PI3K/mTOR pathway was a promising therapeutic approach in patients with acute lymphoblastic leukemia." (PMID 27527856, 2016). "JAK inhibition abolished phosphorylation of JAK/STAT and PI3K/mTOR pathway members in acute lymphoblastic leukemia (ALL), suggesting an interconnection between these signaling networks." (PMID 26275051, 2015). "High activity of the mechanistic target of rapamycin (mTOR) is associated with poor prognosis in pre-B-cell acute lymphoblastic leukemia (B-ALL), suggesting that inhibiting mTOR might be clinically useful." (PMID 25576920, 2015). "Modern genomic techniques and biochemical assays have been used to identify upregulation of the PI3K/mTOR pathway in both pediatric B and T-acute lymphoblastic leukemia (ALL)." (PMID 24904824, 2014). "The PI3K/Akt/mTOR signaling cascade is a key regulatory pathway controlling cell growth and survival, and its dysregulation is a reported feature of B-precursor acute lymphoblastic leukemia (B-pre ALL)." (PMID 25296981, 2014). "We, and others, have previously reported that the mTOR inhibitor everolimus has pre-clinical efficacy and induces caspase-independent cell death in acute lymphoblastic leukemia cells." (PMID 25014496, 2014). "The expression of the mTOR pathway targets p-S6 and p-4EBP1 was characterized in human acute lymphoblastic leukemia cells and normal lymphoid cells by ELISA." (PMID 23573198, 2013).
acute lymphoblastic leukemia (continued). "This three drug combination looks promising since mTOR inhibitors have been recently shown to work synergistically with methotrexate in the treatment of lymphoblastic leukemia." (PMID 19660129, 2009). "In addition, the mTOR inhibitor, everolimus, triggers cell paraptosis in childhood acute lymphoblastic leukemia." (PMID 35646704, 2022). "Some acute lymphoblastic leukemia patients may have some alterations in the PI3K/AKT/mTOR signaling pathway, and BEZ235 had promising effects in this small subset of patients." (PMID 36539659, 2022). "Several chemo-resistance mechanisms including the Bcl-2 protein family overexpression and constitutive activation of the PI3K/Akt/mTOR signaling have been documented in acute lymphoblastic leukemia (ALL), encouraging targeted approaches to circumvent this clinical problem." (PMID 26392332, 2015). "Another MTOR inhibitor, everolimus, also induces autophagy and cell cycle arrest and improves the median survival of mice harboring human childhood B-cell progenitor acute lymphoblastic leukemia." (PMID 25375091, 2014). "While the PI3K/Akt/mTOR pathway is a well-established drug target in T-cell acute lymphoblastic leukemia (T-ALL), the contribution of the Hedgehog (Hh) pathway in T-ALL malignancy remains poorly defined." (PMID 41439992, 2025). "Some studies have shown that PTEN deficiency in tumor suppressor genes leads to the constitutive activation of the PI3K/Akt/mTOR pathway in T-cell acute lymphoblastic leukemia (T-ALL) and is related to the poor prognosis of patients with T-ALL." (PMID 38286894, 2024). "Combining BEZ235 with dexamethasone in acute lymphoblastic leukemia (ALL) showed that along with inhibiting the PI3K/AKT/mTOR pathway, antileukemic effects of dexamethasone were improved in vitro and in vivo." (PMID 37046703, 2023). "let-7a and miR-21: This study describes an mTOR–let-7/miR21–CDK6 axis in murine thymic T-cell acute lymphoblastic leukemia/lymphoma tumors (T-ALL/LBL)." (PMID 34439268, 2021). "mTOR signaling has been particularly well documented in B-cell and T-cell acute lymphoblastic leukemias (B-ALL, T-ALL)." (PMID 34408976, 2021). "TSAIII show the antitumor effect on inducing cell apoptosis and autophagy in T cell acute lymphoblastic leukemia (T ALL) Jurkat cells through the inhibition of PI3K/Akt/mTOR pathway." (PMID 33799345, 2021). "There was an enrichment of hematological malignancies that were sensitive to AKT and mTOR inhibition, with the greatest degree of sensitivity observed in T-cell acute lymphoblastic leukemia (T-ALL)." (PMID 26989080, 2016). "The major regulators of human acute lymphoblastic leukemia (ALL) cell growth and survival mediate their effects through the phosphoinositide 3-kinase (PI-3K)/mammalian target of rapamycin (mTOR) pathway." (PMID 25361005, 2014). "Using Jurkat cells, a PTEN-deficient acute lymphoblastic leukemia cell line rendering AKT signaling pathways autoactivated, we now provide evidence that NVP-BGT226 is capable of inhibiting oncogene-driven PI3K/AKT/MTOR signal transduction pathways in acute leukemia." (PMID 23705826, 2013). "IL7R activation is well documented in hematological malignancies such as acute lymphoblastic leukemia, where it drives pro-survival and proliferation pathways (notably via JAK/STAT, MAPK/ERK, and PI3K/AKT/mTOR signaling)." (PMID 41249788, 2025). "In conclusion, our data show that TR inhibited cell proliferation and induced apoptosis and autophagy through inhibiting the PI3K/AKT/mTOR and Ras/Raf/MEK/ERK signaling pathway in acute lymphoblastic leukemia cells." (PMID 33923896, 2021). "The PI3K pathway plays a role in dexamethasone resistance in acute lymphoblastic leukemia and inhibition of AKT or mTOR reverses dexamethasone resistance." (PMID 33597638, 2021).
acute lymphoblastic leukemia (continued). "Previous work in our lab established the efficacy of asTORi in models of pre-B acute lymphoblastic leukemia and demonstrated reduced hematotoxicity and immunosuppression compared to rapamycin or dual PI3K/mTOR inhibitors." (PMID 24586420, 2014). "Interestingly, aberrant NOTCH signaling is observed in both human and murine T cell acute lymphoblastic leukemia (T-ALL), and NOTCH inhibition in T-ALL lines suppresses mTOR activation by inhibiting c-MYC expression." (PMID 25653651, 2014). "In acute lymphoblastic leukemia (ALL) cell lines, AICAR induced dose- and time-dependent cell growth inhibition, leading to increased AKT phosphorylation and decreased mTOR phosphorylation." (PMID 23875169, 2013). "A small molecule that combines mTOR inhibition and degradation of CDK8 (YKL-06-101) induced cell death in human leukemic cells, representing a potential therapeutic strategy for treating acute lymphoblastic leukemia (ALL) patients." (PMID 39800748, 2025). "Indeed, in acute lymphoblastic leukemia (ALL), obatoclax provokes disruption of the interaction between MCL1 and BECN1, inactivation of MTOR, and activation of the necroptotic cell death." (PMID 34830777, 2021). "Chronic myeloid leukemia (CML) and Ph+ acute lymphoblastic leukemia (ALL) are characterized by the presence of the BCR-ABL oncoprotein, which leads to activation of a plethora of mitogenic and pro-survival pathways, including the mTOR signaling cascade." (PMID 31546746, 2019). "Chronic myeloid leukemia (CML) and Ph+ acute lymphoblastic leukemia (ALL) are characterized by the presence of the BCR-ABL oncoprotein, which leads to activation of a plethora of pro-mitogenic and pro-survival pathways, including the mTOR signaling cascade." (PMID 24260131, 2013). "Within T-cell acute lymphoblastic leukemia (T-ALL), Notch signaling has demonstrated modulation over phosphatidylinositol 3-kinase (PI3K), AKT, and mTOR." (PMID 32498424, 2020). "Activation of AMPK or conversely inhibition of mTOR appear therefore as pertinent therapeutic options for the treatment of BCR-ABL expressing malignancies raising the potential use of AMPK activators such as Aca or Metformin in the treatment of refractory CML and Ph(+) acute lymphoblastic leukemia." (PMID 31881723, 2019). "In acute lymphoblastic leukemia Philadelphia chromosome-positive (Ph + ALL), it was demonstrated that curcumin potentiated the efficiency of imatinib by inhibiting the activation of the AKT/mTOR signaling and by down-regulating the expression of the BCR/ABL gene." (PMID 30045750, 2018). "The finding that rapamycin can sensitize cancer cells to apoptosis, independent of mTOR inhibition, was confirmed in childhood acute lymphoblastic leukemia (ALL)." (PMID 22087835, 2011). "In human cancer cell lines of acute lymphoblastic leukemia (ALL), AML, cervical, breast, colon, GBM, and kidney, the activity of mTOR is downregulated by MLN4924 in an almost dose-dependent manner, as evidenced with dephosphorylation of mTOR downstream targets such as p70S6 kinase." (PMID 32983997, 2020).